FAM156B (family with sequence similarity 156 member B)
Synonyms: TMEM29B
Tractability: Antibody: UniProt predicts a signal peptide or a membrane-spanning region.
Gene: Protein-coding gene on chromosome X (52,891,306 to 52,908,560, forward strand). Ensembl gene ENSG00000179304.
Subcellular location: Membrane
Gene Ontology:
Molecular function: protein binding
Cellular component: nuclear envelope; membrane
Homologues: Orthologues: chimpanzee FAM156A (99% identical), macaque FAM156A (96% identical), dog FAM156A (69% identical), mouse Vcf2 (53% identical), rat Vcf2 (52% identical). Paralogues in human: FAM156A (100% identical).
Diseases named in the same sentence as FAM156B in open-access papers:
FAM156B is named in the same sentence as 3 diseases in open-access papers, as found by Europe PMC text mining. Sharing a sentence is not in itself a finding about the gene and the disease. The quoted sentences say what the papers report.
colorectal cancer (1 paper, 2021). A primary or metastatic malignant neoplasm that affects the colon or rectum. "Our results showed that the methylation of FAM156B, PPP1R3F, and PIH1D3 genes in blood leukocytes is significantly associated with colorectal cancer (CRC) risk and may be potential biomarkers for CRC risk." (PMID 34145793, 2021).
cancer (1 paper, 2021). A tumor composed of atypical neoplastic, often pleomorphic cells that invade other tissues. "As for the important role of the TMEM family in cancer progression, the positive association between FAM156B methylation and CRC risk may imply the effect of FAM156B in CRC pathology." (PMID 34145793, 2021). "To date, the research about the associations between FAM156B, PIH1D3, and PPP1R3F and cancer mainly focus on the gene expression and conducted on tumor tissue and cell lines, the relationship between methylation of FAM156B, PIH1D3, and PPP1R3F and cancer risk and prognosis is still unclear." (PMID 34145793, 2021).
FAM156B also shares sentences with these, for which no sentence is quoted: tumor (1 paper).